ATR (ATR checkpoint kinase)
Diseases named in the same sentence as ATR in open-access papers (continued):
Sharing a sentence is not in itself a finding about the gene and the disease.
tumor (continued). "The evidence suggests that WEE1 inhibition impairs the RS response activated by ATR, and thus increases tumor cell radiosensitivity." (PMID 35875060, 2022). "Loss of ARID1A function compromises DNA damage repair and increases the reliance of tumor cells on ATR-dependent DNA repair pathways." (PMID 36249060, 2022). "ATR inhibition and radiation drive immune cell infiltration via tumor cell-intrinsic cytokine release to boost immunogenic response to radiotherapy and modulate the radiation-induced inflammatory TME." (PMID 35875060, 2022). "Several studies have demonstrated that ATR inhibition is selectively toxic to tumor cells, with high levels of oncogene-induced replication stress." (PMID 35053435, 2022). "Inhibition of WEE1 impairs RS response activated by ATR, and thus increasing tumor cell radiosensitivity." (PMID 35875060, 2022). "Our group reported that loss of MGMT expression via MGMT promoter silencing modulates activation of ataxia telangiectasia and RAD3 related protein (ATR) in response to TMZ treatment, which is associated with synergistic tumor-cell killing." (PMID 35388070, 2022). "Elevated ATM or ATR signaling leads to an increase in genes that suppress the tumor p21 and p27, resulting in the induction of cell cycle arrest." (PMID 35222644, 2022). "Characterization of mice undergoing prolonged ATR inhibition therapy indicated minimal tumor burden and a further increase in γH2AX induction, indicating greater DNA damage." (PMID 35510955, 2022). "Four carriers of germline mutations had additional somatic DDR mutations in the primary tumor: ERCC4; BRCA1, ATM, FANCD2, and MLH1; BRCA1; and BRCA2, RAD50, and ATR." (PMID 36446793, 2022). "Compared with normal patients, we found that the expression level of ATR in the stromal cells (fibroblasts, epithelial cells, and endothelial cells) of tumor patients was low." (PMID 35712480, 2022). "Tumor cells often exhibit a greater reliance upon ATR function than normal cells, a phenotype that can be exploited via small molecules, ATR inhibitors (ATRi), that inhibit ATR kinase activity." (PMID 36273494, 2022). "The ATP-TCA assay shows that the ATR inhibitor VE-822 has tumor suppression rates by a factor of about 5 higher in ARID1A negative compared to ARID1A positive CRC cells." (PMID 36249060, 2022). "Die darauffolgende Aktivierung von ATR und Chk1 reduziert den RS und ermöglicht es dem Tumor, mit dem erhöhten genotoxischen Stress umzugehen." (PMID 36006470, 2022). "The preclinical experiments have supported the combination of adavosertib with olaparib and/or ATR inhibitor for synergistic anti-tumor effect." (PMID 34269904, 2021). "Another critical kinase in DDR is ATR; the ATR inhibitor performs radiosensitization to tumor alongside remarkable infiltration of CD3+ and NK cells in TME through activation of STING and inducing IFN response." (PMID 35265630, 2021). "Cancer cells often show elevated replication stress due to, for example, oncogene expression or tumor hypoxia, which likely provides sensitivity to ATR or WEE1 inhibitors." (PMID 34359691, 2021). "Non-malignant cells possess a functional G1-checkpoint, in contrast to most NSCLC cells, it is proposed that selective tumor radiosensitization can be achieved by abrogation of the G2-checkpoint using inhibitors of ATM or ATR." (PMID 34198619, 2021). "These mouse tumour transcriptomic responses are also in keeping with our phosphoproteomics analyses which identified E2F3 as a phosphorylation target of ATR activity." (PMID 34819497, 2021). "Using RNA-Seq, proteomics and phosphoproteomics we characterize NB cell and tumour responses to ATR inhibition, identifying key components of the DNA damage response as ATR targets in NB cells." (PMID 34819497, 2021).
tumor (continued). "Expression of the G2/M checkpoint protein p21 increased in tumours treated with ATR inhibitor, while levels of both Top2A and the apoptosis inhibitor Survivin decreased, in agreement with RNA levels." (PMID 34819497, 2021). "The ATR molecular pathway regulates cell DNA damage repair through a variety of cytokines, thus leading to the development of normal cells into tumor cells." (PMID 34484285, 2021). "In mice, where ATR expression has been reduced by 90% (“hypomorphic”), the tumor growth elicited by the expression of oncogenes was reduced, with minimal impact on normal tissue homeostasis." (PMID 35008191, 2021). "At first sight, this is an unexpected result since ATM/ATR inhibitors are generally thought to sensitize tumor cells to genotoxic agents." (PMID 33808326, 2021). "CHK1 and CHK2, which can be activated by ATM/ATR kinase, play an important role in DNA damage checkpoint control and tumor inhibition." (PMID 33431817, 2021). "In concordance with the in vitro data, a significant inhibitory effect of the ATR inhibitor on tumor growth was only seen in HPV-negative CAL27 xenografts." (PMID 33546122, 2021). "Remarkably, a 2-week combined ATR/ALK inhibition protocol leads to complete tumor regression in two independent genetically modified mouse NB models." (PMID 34819497, 2021). "Another approach being explored in our NCI clinic is to combine ATR inhibitors with tumor-targeted DNA damaging agents, such as tumor-targeted TOP1 inhibitors (TTT is)." (PMID 34572827, 2021). "Phosphoproteomics and RNA-Seq analyses identified a strong E2F response in treated cells and tumours, as well as key targets of ATR activity in response to replication stress in NB cells (including FANCD2, FANCI, ATRX and DCK)." (PMID 34819497, 2021). "In our study of tumor recurrence, a significant correlation with RFS was observed in gene mutations (ATR, ERBB3, KDR, and MUC6) and fusions (GOPC-ROS1 and NTRK1-SH2D2A)." (PMID 34599262, 2021). "For instance, genes with positive correlation to ATR expression in NB tumours are similarly and strongly enriched for cell cycle-related targets of E2F transcription factors (Padj = 1.30e-15) and G2/M checkpoints (Padj = 2.60e-14)." (PMID 34819497, 2021). "When compared to the vehicle-treated controls, ATR inhibition alone significantly reduced the tumor volume of the HPV-negative CAL27 model from 22 days after the start of treatment." (PMID 33546122, 2021). "Once tumor cells possess ARID1A mutations, subsequent ATR inhibition initiates premature mitotic entry, genomic instability, and apoptosis." (PMID 33513745, 2021). "Confirming tumor volumes, the mice receiving 673A and the ATR inhibitor AZD6738 demonstrated the greatest reduction in tumor weights." (PMID 33664846, 2021). "As such, MCC tumor cells are under significant replication stress and should be more dependent upon ATR to induce the DDR in S/G2 phases to prevent premature entry to mitosis and subsequent cell death." (PMID 34298632, 2021). "For instance, studies have reported the existence of a DNA-PK-Chk1 backup pathway that can mediate resistance to ATR inhibitors in tumor cells with lower levels of replication stress, arguing for the simultaneous targeting of ATR with DNA-PK or Chk1." (PMID 34572908, 2021). "The rapid tumour shrinkage observed on ATR inhibition suggests a strong tumour and potentially host response that was identified as inflammatory signatures in our RNA-Seq analyses." (PMID 34819497, 2021). "Synergy between 673A and ATM or ATR inhibitors was evaluated using the Chou-Talalay method and confirmed in vivo using cell line xenograft tumor studies." (PMID 33664846, 2021). "We observed that ATR or CDC7 inhibition led to increased DNA damage in tumor cells, as measured by γH2AX staining." (PMID 34663432, 2021).
tumor (continued). "Here, we report the results of preplanned exploratory correlative studies on tumor specimens from study subjects and demonstrate that a genomic biomarker of RS is associated with outcome to gemcitabine alone and may predict which patients benefit from addition of the ATR inhibitor berzosertib." (PMID 34552099, 2021). "Remarkably, a 14 day combined ATR/ALK inhibition therapeutic protocol completely ablated tumours in all ALK-driven-NB GEMMs treated." (PMID 34819497, 2021). "Recent studies revealed that ARID1A-deficient tumors are sensitive to PARP inhibitors and ATR inhibitors, and the combination of PARP inhibitors and ionizing radiation in the treatment of tumor cells with ARID1A deficiency has a selective and high efficiency." (PMID 34671561, 2021). "ATR-defective cells also are defective in neuronal migration during development and in metastatic dissemination from circulating tumor cells." (PMID 32973141, 2020). "In another study, it was shown that olaparib, after 5 days of treatment in the 0.1–1 μM range of concentration, was more cytotoxic in BRCAMUT cells (PEO-1, JHOS4) compared with HR-proficient cells (PEO4REV, WO-20 ATR/CHK1 primary tumor cultures, BRCAWT)." (PMID 33352723, 2020). "Previously, tumor cells with genome instability due to defective homologous recombination were shown to depend on the ATR and WEE1 replication checkpoint kinases for their survival." (PMID 33028815, 2020). "We previously showed that PARPi treatment activates ATR/CHK1 and ATRi added to PARPi treatment decreased ATR/CHK1 signaling, release of G2/M checkpoint, increased DNA breaks, and tumor regression in BRCA deficient in vitro and PDX models." (PMID 32709856, 2020). "As an extension to our in vitro data, we further tested the effects of the ATR inhibitor AZD6738 on POLD1R689W/- cells in a murine xenograft tumor model in vivo." (PMID 33144657, 2020). "ATR inhibitors have the potential to show preferential cell killing of tumor cells where ATM is defective or where replicative stress is high." (PMID 32316968, 2020). "This differential expression was obtained in 9 out of 10 pairs, while in the 10th pair, the ATR level was similarly low in both tumor and normal tissues." (PMID 32414408, 2020). "Given our finding that NOTCH1 promotes BRCA1-deficient tumour growth by activating ATR–CHK1 and inducing EMT, we inhibited the ATR/CHK1 pathway in combination with a low dose of cisplatin to effectively kill TNBC in our mouse model and PDX model." (PMID 32591500, 2020). "Tumor tissues from treated mice showed a decrease in phospho-ATR compared with untreated controls, which validate the on-target effect of VX-970." (PMID 32001675, 2020). "In this review, we make a case that this anti-apoptotic role of cis-ATR supports oncogenesis, while Pin1 that drives the formation of trans-ATR suppresses tumor growth." (PMID 32426354, 2020). "The study further showed that DNA-damaging agents result in an induction of PD-L1 expression on tumor cells, and this was prevented by depletion or pharmacological inhibition of ATR." (PMID 33224881, 2020). "As previously reported for subcutaneous tumours, ATR inhibition sensitised LL2-luc subcutaneous tumours to IR." (PMID 32546832, 2020). "Prexasertib stimulates a tumor in terms of sensitivity to other DNA repair agents, blocking the ATR/CHK1 pathway, thereby increasing replication stress." (PMID 32316968, 2020).
tumor (continued). "Our results confirm that reduced ATM function, which can be partially determined by protein level, confers sensitivity to ATR inhibition in NB as it does in other tumour types." (PMID 32354033, 2020). "In the nude mice, EBV-induced ATR activation promoted subcutaneous transplanted tumor growth, higher expression of Ki67 and lung metastasis via M2-type TAMs recruitment." (PMID 32917854, 2020). "Potentially actionable mutations detected from initial IDHWT tumours included EGFR, PTEN, BRCA1, BRCA2, ATM, and ATR." (PMID 32082376, 2019). "Preclinical trials of ATR inhibitors have demonstrated anti-tumour effects in cancer cells with low MRE11 expression." (PMID 30769804, 2019). "The ATR/ATM pathway is crucial for the survival of tumor cells in responding to DNA replication stress and DNA damage." (PMID 31803607, 2019). "The primary tumor sample with the D850V mutation in PDGFRB had concurrent mutations in PTCH1 (c.961C > A), ATR (c.4704C > G), and CDKN1A (c.419_420delGA)." (PMID 31480474, 2019). "Activation of ATR-mediated signalling is a key compensatory response to mitigate replication stress in MYC overexpressed tumours." (PMID 30746633, 2019). "ATM and ATR protect cells that are obtained from tumor progression by inducing cell cycle arrest and apoptosis in the early phases of tumorigenesis." (PMID 31772936, 2019). "In light of these results, we then performed a clonogenic assay to examine the anti-tumor effect of the combination of a conventional chemotherapeutical drug and the ATR or ATM inhibitor." (PMID 31805725, 2019). "Tumours with high MYC and high ATR expressions were significantly associated with vascular invasion, higher tumour grade, pleomorphism, high mitotic index and high-risk Nottingham Prognostic Index (NPI) (all adjusted p values ≤ 0.01)." (PMID 30746633, 2019). "Targeting the cell cycle checkpoint kinase ATR can be utilized to induce premature mitotic entry and thereby increase the cytotoxicity of PARP inhibitors in HR‐deficient tumor cells." (PMID 31529615, 2019). "It inhibits ATR function in vitro and in cell culture systems, and its oral administration to mice carrying xenografted adenocarcinoma cells reduces tumor growth." (PMID 29977027, 2018). "Using agents such as AZ20 (ATR inhibitor) and ISRIB (inhibitor of eIF2α phosphorylation), this study demonstrates that Chk1 inhibitors are able to prevent tumor-induced bone loss by blocking tumor growth as well as bone resorption." (PMID 29507695, 2018). "The expression of ATR appeared to be higher in the tumor of patients who are over 57 years of age compared to adjacent mucosa (p-value = 0.02)." (PMID 29870526, 2018). "The only gene appeared to be affected by stage was ATR, a significant increase in expression of tumor tissue of the late stage was seen compared to its adjacent mucosa." (PMID 29870526, 2018). "Regarding tumor site, the DNA damage response genes, ATR, ATM and Chk1, showed a difference in their expression." (PMID 29870526, 2018). "In nuclear PTEN-negative tumours, we then investigated the prognositic significance of ATR- cytoplasmic pCHK1ser345 co-expression." (PMID 29396668, 2018). "In tumours with low nuclear PTEN, high ATR and/or high pCHK1ser345 level was also linked to higher grade, larger tumour size and poor survival (all p values < 0.05)." (PMID 29396668, 2018). "Consistent with this, decreased levels of ATR and treatment with ATR inhibitors (ATRi), presently being tested in phase I–II clinical trials, suppress tumour growth, whereas an extra copy of Chk1 facilitates cellular transformation." (PMID 29950452, 2018). "Tumours with high-ATR and -cytoplasmic pCHK1ser345 expression had the worst survival compared to those with low-ATR and-cytoplasmic expression (p = 0.014)." (PMID 29396668, 2018).
tumor (continued). "Our new finding will provide valuable information for a specific type of adjuvant combination therapy that combines the inhibitors of Cdc7, HSP90, and/or ATR to block DNA synthesis and exploit defects in DNA repair/checkpoint of tumor cells." (PMID 29209046, 2017). "In vivo, the ATR inhibitor AZ20 was found to have anti-tumour efficacy against nude mice bearing LoVo colorectal tumour xenografts, with K-Ras mutation and expression of c-Myc, H-Ras, N-Ras, Myb and Fos oncogenes." (PMID 28448462, 2017). "To explore the contribution of the downstream signaling pathway of UCA1 to the tumor suppressor function of ATR, we identified the potential sponge function of UCA1 on miRNAs." (PMID 28209917, 2017). "Inhibition of ATR was assessed by measuring changes in levels of phosphorylated-CHK1 (pCHK1) in paired pre-dose/post-dose tumour biopsies in three patients." (PMID 28448462, 2017). "Due to the central role in the DNA damage response, different cell cycle checkpoint inhibitors (ATM/ATR/CHK1/CHK2/WEE1 inhibitors) have been developed to specifically inhibit the mechanisms by which tumor cells respond to DNA damaging agents." (PMID 28356161, 2017). "Now that we have established spDSB-activated ATM/ATR to be important for sustaining tumor growth, the next logical question is which downstream factors of ATM are responsible for supporting tumorigenicity." (PMID 28337983, 2017). "Accordingly, ATR expression was reduced in cells and in tumor xenografts, when treated with platinum + PD." (PMID 28778953, 2017). "The genes most frequently targeted by MSI are RAD50 (16% of MSI-H tumours), ATR (15%) and RBBP8 (10%)." (PMID 28585546, 2017). "The ataxia telangiectasia and rad3-related (ATR) pathway is the primary response to replication stress in tumor models." (PMID 26810087, 2016). "In these studies, Gli1 expression has been shown to suppress replication stress in tumor cells by regulating ATR mediated Chk1 phosphorylation through transcriptional regulation of Bid." (PMID 26988232, 2016). "At the termination of the protocol, day 28, mice treated with cognate ATR had the smallest tumor burden compared to mice receiving 2C T cells only, control animals and mice treated with non-cognate ATR." (PMID 27602488, 2016). "A clear decrease in the levels of both phosphorylated ATR and Chk1 were observed in a tumor treated with VX-970." (PMID 27839769, 2016). "While Inhibition of Gli1 in tumor cells reduced Bid levels and its association with RPA-ATRIP complex leading to abrogation of ATR-mediated Chk1 phosphorylation." (PMID 26988232, 2016). "The ability of ATR to induce redirected lysis in vivo was studied by analyzing Raji tumor growth in SICD/beige mice." (PMID 27602488, 2016). "ATR stably bind tumor cells and CTL in a dose dependent fashion and stimulate antigen-specific conjugate formation between those cells." (PMID 27602488, 2016). "Using a systems pharmacology approach, we have extended an existing PK-PD model of tumor growth with a mechanistic model of the cell cycle, enabling simulation of mono and combination treatment with the ATR inhibitor AZD6738 and ionizing radiation." (PMID 26310312, 2015). "In this report we have shown for the first time that pre-treatment of the ATR inhibitor VE-821 clearly enhanced the effect of carbon ion irradiation in human tumor cells." (PMID 26286029, 2015). "VX-970 was shown to block ATR activity in tumours and dramatically enhance the efficacy of cisplatin across a panel of patient-derived primary lung xenografts." (PMID 26610585, 2015). "In accordance with ATR's involvement in prosurvival pathway, ATR inhibition has been suggested as a new approach to increasing the sensitivity of tumor cells to radiochemotherapy." (PMID 26000719, 2015).